SNORD91A (small nucleolar RNA, C/D box 91A)
Synonyms: HBII-296a
Gene: Small nucleolar RNA gene on chromosome 17 (2,330,180 to 2,330,370, reverse strand). Ensembl gene ENSG00000212163.
Gene Ontology:
Biological process: RNA processing
Cellular component: nucleolus